CD4 (CD4 molecule)
Diseases named in the same sentence as CD4 in open-access papers (continued):
Sharing a sentence is not in itself a finding about the gene and the disease.
tumor (continued). "Additionally, these MoDCs increased the frequency of CD4+Granzyme B+ cells, a subset of cytotoxic CD4+ T cells that may enhance anti-tumor immunity." (PMID 40574085, 2025). "Interestingly, neutralization of CD4+ T cells in mice injected with Plac1‐OE cells reduced both tumor volume (p = 0.0493) and weight (p = 0.0479) to levels comparable to those in the Plac1‐NC group (both tumor volume and weight: ns between groups)." (PMID 40056047, 2025). "Furthermore, with the introduction of stable multiplex techniques, combined with advanced image analyses, it is possible to locally define the spatial relations of immune cells to tumor cells or immune cell subsets (CD8 + effectors cells or CD4 + memory T-cells) to each other." (PMID 40029549, 2025). "Moreover, TAGAP could promote the differentiation of CD4+ T cells into Th1/Th17 cells with pro-inflammatory and anti-tumor effects, while inhibiting their differentiation into Tregs with inhibitory immune responses." (PMID 39998561, 2025). "Additionally, recent evidence suggests that expanded clones of HIV-infected CD4 + T cells infiltrating tumor tissues may contribute to low-level viremia in patients with malignancies." (PMID 40251661, 2025). "Similarly, when CD4+ helper T cells compete with tumor cells and myeloid cells for polyamine uptake, the polyamine deficiency can cause problems with differentiation of T cells into subtypes (TH1, TH2, TH17, and Tregs), promoting immunosuppression and tumor growth." (PMID 40927726, 2025). "Of note, M002 treatment increased the frequency of CD4+ T cells infiltrating the tumor in both mouse strains compared to saline treatment, which may partially explain why M002-treated Tbx21fl/flCD4cre mice still had more prolonged survival than saline-treated Tbx21fl/flCD4cre mice." (PMID 39885128, 2025). "Given the importance of IFN-γ and CD8+ T cells to ICI anti-tumor immune responses, we focused on the less explored role of CD4+ T cells with the aim of identifying driving immune mechanisms that could be targeted in patients with cancer to reduce IrAEs while preserving efficacy." (PMID 40626363, 2025). "Hence, cDC2 depletion in the tumor might reflect their migration to lymph nodes to present antigen to CD4+ T cells." (PMID 40573908, 2025). "Notably, exosomes derived from Rab27a‐overexpressing lung cancer cells not only promote upregulation of MHC class II, CD80, and CD86 on DCs, but also facilitate CD4+ T cell proliferation and type I cytokine secretion, culminating in effective tumor growth inhibition in vivo." (PMID 41256221, 2025). "In most cancer types, PTEN loss was associated with a higher abundance of CD4+ lymphocytes, M1 macrophages, and FoxP3+ T regulatory cells, along with increased expression of immune checkpoints such as LAG3 and IDO1, indicating an immunosuppressive tumor microenvironment." (PMID 40650023, 2025). "Moreover, the expression level of CD39 was altered in several T cell subtypes from tumour–adjacent bowel, such as CD4+ Tem, CD8+ Tem, CD8− γδ T cells and especially CD4+ Treg, indicating that CD4+ Treg promoted the immune‐suppressive environment during tumour progression at the margin of tumour." (PMID 39934971, 2025). "Additionally, this finding in epithelial cells complements recent scRNAseq data in tumor-infiltrating immune cells, wherein conventional CD4+ T cells were found to differ in their differentiation trajectory by HPV status, having downregulated interferon responses and effector memory phenotypes." (PMID 40284904, 2025). "This inefficiency could suggest a reduction in antigen presentation capacity due to the loss of B7.1 and B7.2 from antigen-presenting cells, which may impair the activation of anti-tumor CD4 T cells and contribute to the development of an immunosuppressive tumor microenvironment." (PMID 39741180, 2025).
tumor (continued). "Further characterization of these immune cells is required to determine whether they represent pro-or anti-tumor infiltrate, however our finding that Treg-like CD4 + FoxP3+ cells were more prevalent in tumors bearing E. faecalis indicates that at least a portion of the infiltrate was pro-tumor." (PMID 41322090, 2025). "In addition, high expression of CXCR4 on the surface of activated CD4 + T cells may lead to the production of cytokines that affect T-cell activation, thereby promoting the initiation of an effective anti-tumour response." (PMID 41243106, 2025). "The favorable impact of high CD19+ B cells, CD4+ T cells, and the CD4+/CD8+ ratio, along with the adverse association of elevated CD8+ T cells with outcome, aligns with findings in other cancers where such an immune profile indicates tumor-induced immunosuppression." (PMID 41244913, 2025). "Depending on the subtype, CD4+ T-cells may either promote or inhibit tumor progression." (PMID 40725022, 2025). "DAC/IL-33 and PD-1 mAb strongly synergized to increase tumor-infiltrating immune effector cells (i.e., CD4 T cells, CD8 T cells and eosinophils) and intratumoral expression of effector molecules (i.e., IFN-γ, granzyme B, perforin and TNF-α) which may account for therapeutic efficacy." (PMID 40317004, 2025). "However, the strength of IL-6 signals in CD4+ T cells versus tumor cells could differ, and targeting IL-6 to inhibit GBM tumor growth may need to consider its impact on CD4+ T cells, which needs to be further explored." (PMID 39885128, 2025). "Furthermore, significant correlations emerged among FAP + CAFs, TILs, and CD68 + cells, and the co-occurrence of elevated FAP + CAFs, T-cytotoxic (CD8 +), T-regulatory (CD4 + FOXP3 +) cells, and macrophages (CD68 +) at the tumor center were independently associated with worse CSS." (PMID 39751643, 2025). "In contrast, deletion of the lipid phosphatase PTEN in Tregs leads to the hyperactivation of selective effector CD4 + T cell responses but also unleashes anti-tumor immune responses, suggesting that phospholipid signaling may fine-tune Treg function in diverse contexts." (PMID 40215232, 2025). "Single-cell analysis has shown that the proportion of T cells in the NPC tumor microenvironment is higher than in other cancers, such as non-small cell lung cancer, colorectal cancer, and pancreatic ductal adenocarcinoma, with the majority of T cells being CD4+ and CD8+ subsets." (PMID 40444078, 2025). "As many of the Py230 primary tumours in our immune competent mouse model underwent spontaneous regression or failed to develop at all after cancer cell inoculation, the immune effector populations of CD4+ and CD8+ T cells from the spleen were examined using flow cytometry." (PMID 40172096, 2025). "Certain probiotics, such as Lactobacillus casei, Lactobacillus rhamnosus, and Saccharomyces boulardii, may enhance CD8+ and CD4+ T-cell infiltration in the tumor environment, potentially boosting progression-free and overall survival in patients not eligible for curative surgery." (PMID 41471890, 2025). "Thus, functional studies across 3 unique patients, distinct from scRNA-seq or flow cytometry cohorts, validate that KLRG1–E-cadherin interactions can inhibit MHC class II–dependent autologous tumor killing by cytotoxic CD4+ T cells, in a mechanism that is distinct from and complements PD-1 blockade." (PMID 40299576, 2025). "The significant increase of CD4+ naïve T cells may indicate compromised antigen presentation or an immunosuppressive environment that obstructs early T cell activation, thereby undermining effective anti-tumor immunity." (PMID 40842994, 2025). "BRI3BP expression correlated strongly with immunosuppressive subsets—Th2 cells (r = 0.482, P < 0.001) and CD4 + T cells (r = 0.208, P = 1.00e-04), indicating that BRI3BP may foster an immunosuppressive tumor microenvironment linked to resistance to immune-checkpoint blockade in HCC35." (PMID 41174063, 2025).
tumor (continued). "Moreover, S100A14 expression showed the highest positive correlation with the percentage of CD8+ T cells in the tumors (R = 0.30, p = 0.016), whereas a negative correlation (R = −0.29, p = 0.024) was observed in the percentage of CD4+ T cells and macrophages within tumor samples." (PMID 40806532, 2025). "Moreover, Cxcr3-expressing Th1-like CD4+ T cells have been shown to be induced as nanoparticles that target tumor-draining lymph nodes, which is consistent with our nanomedicine that targets the tumor niche." (PMID 40530387, 2025). "VGF was significantly positively correlated with activated mast cells and activated CD4 memory T cells, and negatively correlated with Tregs, suggesting that VGF may be linked to a more pro‐inflammatory and less immunosuppressive tumor environment." (PMID 40600620, 2025). "Moreover, HA@CD36i‐TR@siSCD1 had a potent immune‐enhancing effect, increasing the proportion of CD8+ T cells, decreasing the number of CD4+FoxP3+ Treg cells, promoting the release of the tumor killer factors TNF‐α and IFN‐γ, and transforming refractory PCa from “cold” tumors to “hot” tumors." (PMID 39736148, 2025). "Among CD4+ T cell subsets, T follicular helper (Tfh) cells in TDLNs interact with B cells to deliver survival signals, promoting their proliferation, differentiation, and affinity maturation, thereby enabling B cells to produce high-affinity antibodies against tumor antigens." (PMID 40904508, 2025). "However, the role of LTβR in CD4+ T cell differentiation and tumor immunity is unclear." (PMID 40436857, 2025). "Additionally, we investigated whether CD8+ or CD4+ T cells contributed to ULBP2-mediated tumor growth." (PMID 40243581, 2025). "In all investigated OC-associated compartments, CD4+ T cells displayed higher percentages than CD8+ T cells, with a significantly increased proportion of blood-circulating CD4+ T cells (76.77 ± 3.03% of CD3+ T cells) and least tumor-infiltrated CD4+ T cells (47.99 ± 5.20% of CD3+ cells)." (PMID 41221283, 2025). "Moreover, the proportion of Tregs (CD3+CD4+FoxP3+) in the combined treatment group significantly decreased compared to that in the model (p < 0.001) and PDT (p < 0.05) groups, confirming a reduction in tumor-associated immunosuppression." (PMID 40746718, 2025). "For instance, the ratio of CD4+ memory resting T cells decreased in the tumor group, indicating that tumor cells may reduce the immune capacity of the body through immune evasion mechanisms, alterations in the immune microenvironment, and exhaustion due to chronic antigen stimulation." (PMID 40002911, 2025). "Thus, in the context of gastric cancer, tumor-activated γδ T cells not only kill tumor cells efficiently, but also strongly induce primary CD4+ and CD8+αβ T cells proliferation and differentiation, increasing their cytotoxic functions and abrogating immunosuppression by T regulatory cells." (PMID 40422223, 2025). "The absence of a significant association with CD4+ TILs may be due to variations in the evaluation criteria, organs, and tumor types." (PMID 40586978, 2025). "Numerous reports have described a role of CCR10 and its ligands in cancer although the benefits of CCR10 antagonism may be cancer-dependent: the receptor can have protumoral effects when expressed on regulatory T cells or tumor cells or antitumoral effects when expressed on CD4+ and CD8+ T cells." (PMID 40975172, 2025). "In the subcutaneous MC38 tumor model, anti–PD-1 treatment caused tumor regression, while progressive tumor expansion was observed in the Gsdmdfl/fl CD4cre mice after anti–PD-1 treatment, indicating the importance of GSDMD activation in CD4+ T cells for the therapeutic effectiveness." (PMID 40759573, 2025).
tumor (continued). "Studies have shown that nCRT-induced tumor cell necrosis and apoptosis release a significant amount of tumor antigens, which are captured and presented to T cells by antigen-presenting cells (such as dendritic cells), subsequently activating CD4+ and CD8+ T cells and triggering an immune response." (PMID 40936903, 2025). "Additionally, differences in the tumor microenvironment are evident, with females exhibiting increased CD4+ and CD8+ T cell infiltration and distinct gene expression profiles that may influence tumor aggressiveness and therapeutic response." (PMID 40807160, 2025). "Therefore, CD4 + T lymphocytes demonstrate a positive anti-tumor effect in EC, and elevated levels of CD4 + expression may be a good prognostic marker." (PMID 40587482, 2025). "Notably, we observed different CD4+ cell infiltration patterns in PyMT tumors with ineffectively αPD1/α4-1BB–treated animals showing infiltration predominantly at the tumor periphery, whereas effectively treated animals exhibited increased infiltration within the tumor core." (PMID 40561008, 2025). "However, the specific role of CD4+ granzyme B+ T cells in tumor immunity remains unclear and warrants further investigation." (PMID 39744218, 2025). "Finally, we investigated whether CD4+ T cells of overexpression or silencing TAGAP could affect tumor progression in vivo." (PMID 39998561, 2025). "In addition, PDL1 in circulating tumor cells and CD4/CD8+ T cell populations may serve as prognostic biomarkers for immunotherapy in metastatic genitourinary cancer patients." (PMID 38783893, 2024). "Thus, while CD8+ T cells target and eliminate tumor cells, the collaborative dynamics with CD4+ T cells are indispensable, underscoring the need for therapeutic strategies that harness the synergistic potential of both T cell subsets to maximize cancer immunotherapy efficacy." (PMID 39438986, 2024). "TDSEVs that carry antigens or antigen MHC complexes may directly transfer these components to antigen presenting cells, increasing the ability of displaying TDSEV-derived tumor antigens on their MHC-I/CD8 or MHC-II/CD4 complexes, and thus controlling tumor-mediated T cell responses." (PMID 38243280, 2024). "Considering the complex spatial structure and tumor heterogeneity of GC cells, we deconstructed immune cell regulation mediated by PRS using single-cell and multiplex immunofluorescence and found that PRS was significantly associated with the infiltration of effector and CD4 T cells." (PMID 38773976, 2024). "In this study, we radiolabeled anti-mouse and anti-human CD4-targeting Mbs with 89Zr using the chelator desferrioxamine (dfo) and extensively validated both immunotracers in xenograft, syngeneic, and hCD4 knock-in (KI) tumor mouse models to assess their specificity and cross-species comparability." (PMID 39239511, 2024). "In this context, this article reviews the evidence for this hypothesis regarding the phenotypes and functions of CD4+ T lymphocytes and compares their contribution to maintaining tissue homeostasis in different organs in a steady state and during tumor progression." (PMID 38690280, 2024). "Furthermore, LAG3 has been found to be expressed on tumor‐infiltrating CD4+ and CD8+ T cells." (PMID 39565059, 2024). "Additionally, cucurbitacin B can inhibit the JAK2/STAT3 signaling pathway, reduce the migration and invasion ability of M2-like TAM polarization-induced colon cancer cells, enhance the anti-tumor response, and increase the expression of CD4 and CD8 in the tumor microenvironment." (PMID 39275042, 2024). "However, after Bcl6 knockout, depletion of CD4+T cells could rescue the tumor growth to the level which is comparable to combined depletion of CD4+T cells and CD8+T cells group, while depletion of CD8+T cells could only slightly increase tumor growth." (PMID 38956432, 2024). "Notably, CD4+ T memory cells play a pivotal role in bolstering anti‐tumour responses." (PMID 39031800, 2024).
tumor (continued). "Hence, we speculate that the overexpression of UBE2C inhibits the invasion of B cells and CD4+ T cells, thus accelerating tumor progression in LUAD." (PMID 38370368, 2024). "We observed that CD8 T-cell clusters overlapped with tumour cell clusters to a greater extent than other immune cell types did based on the calculated Dice score for overlap of the corresponding spatial cluster masks (two-tailed Wilcoxon tests, unadjusted: CD4 T cells p = 0.006, B cells p = 1e-4)." (PMID 38879602, 2024). "In addition, to investigate whether acquired immunity affected tumor growth suppression, CD4+ or CD8+ T cell depletion antibodies were administered prior to NIR-PIT in allograft models." (PMID 38555315, 2024). "However, the role of CD4+ T in tumor immunity remains to be explored." (PMID 39697556, 2024). "However, if these cells undergo up-regulation, the excessive presence of CD8+ T cells, CD4+ T cells, and macrophages in cancer can tumor-induced immunosuppression, immune cell exhaustion, regulatory T cell activity, and the up-regulation of immune checkpoints and immunosuppressive molecules." (PMID 38560573, 2024). "The study also found that oral supplementation of Akkermansia muciniphila could restore the efficacy of PD-1 blockade after antibiotic treatment, an effect that depends on IL-12 and is mediated by increasing the infiltration of CCR9+CXCR3+CD4+ T lymphocytes into the tumor bed of mice." (PMID 39885985, 2024). "However, we also observed a decrease, albeit not significant, in conventional T cells that could potentially decrease efficacy of the treatment, as there have been discrepancies regarding the importance of the role of CD4+ versus CD8+ cells in tumor clearance." (PMID 38328418, 2024). "Additionally, although depletion of CD4+ cells weakened the inhibitory effect of combination therapy, the difference was not significant, suggesting a potential auxiliary role for CD4+ T cells in the anti-tumor immune response." (PMID 38630304, 2024). "Although low values of intracellular IL-10 were found in CD4+ T cells, the high values of that cytokine observed in the culture supernatant associated with high IL-4 suggest an anti-inflammatory profile (Th2) promotion by HPV oncogenes present in the transfected A549 tumor cells." (PMID 39599846, 2024). "Similarly, detrimental clustering of tumor cells and CD4 T cells as observed for short-lived patients could be due to CD4 T cells being predominantly composed of regulatory T cells (Treg) that are able to keep the activity of CD8 T cells in check." (PMID 40604303, 2024). "This mode of internalization may activate tumor-specific CD4+ or CD8+ T cells." (PMID 38835772, 2024). "In the tumor microenvironment, PLOD1 expression correlated positively with the infiltration level of various immunosuppressive cells (e.g., monocytes, macrophages and tumor-associated fibroblasts) and negatively with immune-killing cells (e.g., CD8+ T cells, B cells and CD4+ T cells)." (PMID 39767559, 2024). "However, tumor Tregs play a crucial role in suppressing tumor-specific CD8+ T cell responses in tumor-draining lymph nodes, thus impeding antitumor immunity at the initial stages of the immune response triggered by adoptively transferred tumor-primed CD4+ T cells." (PMID 39664195, 2024). "The tumor microenvironment is characterized by an immunosuppressive milieu 40, and the immunoassay results indicated that ABO is linked to cytotoxicity, helper T-cell 2 (Th2), central memory, follicular helper T-cells (Tfh), natural killer (NK) cells, and CD4+ T-cells in BRCA." (PMID 38706896, 2024). "STC1 may influence CD4+ T cells to secrete cytokines, including IL-17, IL-31, and IL-33, which modulate immune responses via autocrine or paracrine mechanisms, thereby either amplifying or suppressing immune activity within the tumor microenvironment." (PMID 39201771, 2024).